KCNT2 (potassium sodium-activated channel subfamily T member 2)
Description:
Sodium-activated and chloride-activated potassium channel. Produces rapidly activating outward rectifier K(+) currents. Contributes to regulate neuronal excitability.
Synonyms: SLICK; Slo2.1; KCa4.2; DEE57; EIEE57; KNa1.2
Tractability: Small molecule: it belongs to a druggable protein family. Antibody: UniProt places it where antibodies can reach, with high confidence; its Gene Ontology location is reachable by antibodies, with high confidence; UniProt predicts a signal peptide or a membrane-spanning region. PROTAC: ubiquitination databases record sites on it.
Gene: Protein-coding gene on chromosome 1 (196,225,779 to 196,609,225, reverse strand). Ensembl gene ENSG00000162687.
Subcellular location: Cell membrane
Subcellular location (Human Protein Atlas): Vesicles
Gene Ontology:
Molecular function: chloride-activated potassium channel activity; intracellular sodium-activated potassium channel activity; protein binding; outward rectifier potassium channel activity
Biological process: potassium ion export across plasma membrane; potassium ion transmembrane transport; potassium ion transport
Cellular component: plasma membrane; membrane
Genetic constraint (gnomAD): Loss-of-function variants: 27 observed, 50.04 expected, observed/expected ratio (o/e) 0.54, 90% interval 0.4 to 0.74. The upper end of that interval is the gene's LOEUF score, 0.74, which puts it in group 3 of 6, group 1 being the genes least tolerant of losing a copy. Missense variants: 365 observed, 553.39 expected, observed/expected ratio (o/e) 0.66, 90% interval 0.61 to 0.72. Synonymous variants: 202 observed, 195.68 expected, observed/expected ratio (o/e) 1.03, 90% interval 0.92 to 1.16.
Homologues: Orthologues: chimpanzee KCNT2 (100% identical), macaque KCNT2 (99% identical), dog KCNT2 (99% identical), pig KCNT2 (98% identical), rabbit KCNT2 (98% identical), mouse Kcnt2 (98% identical), rat Kcnt2 (96% identical), guinea pig KCNT2 (87% identical), tropical clawed frog kcnt2 (87% identical), zebrafish kcnt2a (60% identical), Drosophila melanogaster SLO2 (56% identical), Caenorhabditis elegans slo-2 (44% identical). Paralogues in human: KCNT1 (78% identical), KCNMA1 (21% identical), KCNU1 (19% identical).
Diseases named in the same sentence as KCNT2 in open-access papers:
KCNT2 is named in the same sentence as 40 diseases in open-access papers, as found by Europe PMC text mining. Sharing a sentence is not in itself a finding about the gene and the disease. The quoted sentences say what the papers report.
epileptic encephalopathies (7 papers, 2019 to 2025). "We then searched additional KCNT2 variants in our in-house WES database of a cohort of more than 200 patients with early-onset epileptic encephalopathy (EOEE)." (PMID 32038177, 2020). "In turn, KCNT2 variants, causing epileptic encephalopathies, present with GoF characteristics." (PMID 38003469, 2023). "Here, we have used exome sequencing to identify two novel de novo nonsense and frameshift mutations of the KCNT2 gene in two patients with ascertained EIMFS and with EIMFS-like early-onset epileptic encephalopathies (EOEE), respectively." (PMID 32038177, 2020). "Diseases associated with potassium sodium-activated channel subfamily T member 2 (KCNT2) include early infantile epileptic encephalopathies." (PMID 31557882, 2019).
endometritis (4 papers, 2024 to 2025). An acute or chronic, usually bacterial infectious process affecting the endometrium. "Gene expression levels were considerably higher in endometritis-affected buffaloes than in resistant ones for the genes A2M, TLR2, IRAK3, CCl2, FCAMR, iNOS, ADAMTS20, KCNT2, MAP3K4, MAPK14, FKBP5, and EPHA4." (PMID 38459095, 2024).
developmental and epileptic encephalopathy (3 papers, 2021 to 2023). An epilepsy associated with developmental impairment that may be due to either the underlying etiology or the superimposed epileptic activity, or both. "The KCNT2-associated developmental and epileptic encephalopathy comprises West syndrome, Lennox-Gastaut syndrome as well as epilepsy of infancy with migrating focal seizures." (PMID 35183220, 2022).
melanoma (3 papers, 2019 to 2021). A malignant, usually aggressive tumor composed of atypical, neoplastic melanocytes. "The expression of KCNT2 in melanoma was more downregulated than that of normal tissues at both the transcriptional and the protein level." (PMID 31557882, 2019). "In addition, gray-scale analysis revealed statistically significant differences in the protein expression of STK26 (P = 0.0024) and KCNT2 (P < 0.0001) between normal skin and melanoma." (PMID 31557882, 2019). "Therefore, the expression of KCNT2 may be an indicator of the identification of nevus and melanoma, but further research and large-scale clinical data should be carried out to confirm these hypotheses." (PMID 31557882, 2019). "Our results showed that, similarly to STK26 and KCNT2, the transcription of CASP12 in melanoma was reduced relative to nevus, which might mediate the process of the conversion of nevus to melanoma." (PMID 31557882, 2019).
Alzheimer disease (2 papers, 2021 to 2024). A progressive, neurodegenerative disease characterized by loss of function and death of nerve cells in several areas of the brain leading to loss of cognitive function such as memory and language. "Multiple GWAS studies reported that KCNT2 and DUSP18 are associated with Alzheimer disease, and KCNT2 is also associated with chronotype." (PMID 33314580, 2021).
Intellectual disability (2 papers, 2024 to 2025). "This table summarizes the key findings of studies on Slo2/KCNT1/KCNT2 channels in intellectual disability, with GRADE ratings and rationale highlighting limitations, sample size, model relevance, and translational applicability." (PMID 41189825, 2025). "The search combined relevant keywords and MeSH related to Slo2 channels, KCNT1/KCNT2, sodium-activated potassium channels, intellectual disability, and neurological disorders." (PMID 41189825, 2025).
Lennox-Gastaut syndrome (2 papers, 2020 to 2022). Lennox-Gastaut syndrome (LGS) belongs to the group of severe childhood epileptic encephalopathies. "Two gain-of-function KCNT2 mutations were identified in a patient with West syndrome that evolved to a Lennox-Gastaut syndrome, and in a patient with EIMFS, respectively." (PMID 32038177, 2020).
breast carcinoma (1 paper, 2025). "Breast cancer studies included E1 (KCNMB1), E4 (KCNN3), E9 (KCNH1, KCNK15), E15 (KCNT2), E22 (KCNK5, KCNK15), E33 (KCNQ1-OT1), E38 (KCNMA1), E48 (KCNJ9), and E63 (KCNK12)." (PMID 40867621, 2025).
colitis (1 paper, 2020). Inflammation of the colon. "To exclude the effect of Kcnt2 on innate colitis induction, we established Kcnt2 KO mice via CRISPR/Cas9 technology." (PMID 32796851, 2020). "We observed that Kcnt2−/−Rag1−/− mice did not affect lymphocytes infiltration, colon injury, body weight loss and colitis scores compared with Kcnt2+/+Rag1−/− mice, suggesting Kcnt2 has no influence on innate colitis induction." (PMID 32796851, 2020).
diabetic polyneuropathy (1 paper, 2025). "The locus that showed the strongest association with severity of diabetic polyneuropathy-related pain mapped to the gene KCNT2." (PMID 39471050, 2025). "In the genome-wide association study of diabetic neuropathy (N = 1541), a top significant association was found at the KCNT2 locus linked with pain intensity (rs114159097, P = 3.55 × 10−8)." (PMID 39471050, 2025).
hypertrichosis (1 paper, 2024). Excessive hair growth anywhere on the body. "KCNT2-relevant DEEs partially overlap with the clinical phenotypes of KATP channel diseases, particularly in hypertrichosis and distinctive coarse facial features." (PMID 38510274, 2024).
Hypsarrhythmia (1 paper, 2020). Hypsarrhythmia is abnormal interictal high amplitude waves and a background of irregular spikes. "A third KCNT2 mutation leading to KNa1.2 channels that were no more selective for K+ ions and that became permeable to Na+ ions was identified in a patient with multi-focal epileptogenic activity or hypsarrhythmia." (PMID 32038177, 2020).
malignant migrating partial seizures in infancy (1 paper, 2013). "Moreover, a gain-of-function mutation in the Kcnt1 gene, a gene whose function is closely related to that of Kcnt2, has been recently associated with a childhood epileptic syndrome called malignant migrating partial seizures in infancy (MMPSI)." (PMID 24068938, 2013).
periodontal disease (1 paper, 2025). "The most robust associations found for each phenotype are as follows: DMFT with rs79198416 (near CDC73/KCNT2; p = 7.57E-07), periodontal disease with rs73870587 (DIPK2A, p = 7.38E-08); CIMT with rs113152669 (LRP1Bp = 4.07E-07), and CAC with rs76676138 (CNTNAP2; p = 2.47E-19)." (PMID 41006734, 2025).
neurological diseases (2 papers, 2021 to 2025). "Search terms combined keywords and Medical Subject Headings (MeSH) relevant to Slo2 channels, KCNT1/KCNT2, sodium-activated potassium channels, ID, and neurological disorders." (PMID 41189825, 2025).
neurodevelopmental disorder (1 paper, 2025). A behavioral and cognitive disorder with onset during the developmental period that involves impaired or aberrant development of intellectual, motor, or social functions. "This table presents details of experimental and review studies investigating Slo2 channels and KCNT1/KCNT2-related neurodevelopmental disorders." (PMID 41189825, 2025).
KCNT2 also shares sentences with these, for which no sentence is quoted: epilepsy (3 papers); cancer (2); ischemia (2); lung carcinoma (2); West syndrome (2); acute lymphoblastic leukemia (1); Autoimmunity (1); bipolar disorder (1); channelopathies (1); cocaine dependence (1); developmental delay (1); experimental autoimmune encephalomyelitis (1); Focal Seizures (1); infantile epileptic encephalopathy (1); insomnia (1); Leukoencephalopathy (1); metastatic melanoma (1); neuropathy (1); nevus (1); osteoarthritis (1); Parkinson disease (1); skin cutaneous melanoma (1); tumour (1); viral encephalitis (1).